EGFR (epidermal growth factor receptor)
Diseases named in the same sentence as EGFR in open-access papers (continued):
Sharing a sentence is not in itself a finding about the gene and the disease.
pancreatic cancer (continued). "We also tested the effect of enzastaurin treatment on tumour growth in other EGFR-expressing cancer cell lines, including SKLU-1 and GLC-82 (NSCL cancer) and PACA44, PANC1 and HPAF (pancreatic cancer cells)." (PMID 18665191, 2008). "In a murine model of pancreatic cancer, the BCL-XL promoter was shown to integrate the epidermal growth factor receptor (EGF-R) signal." (PMID 18652674, 2008). "The receptor tyrosine kinase epidermal growth factor receptor (EGF-R) and its ligands are over expressed in pancreatic cancer tissues and in pancreatic cancer cell lines, with coexpression of receptor and ligand correlating with tumor invasiveness." (PMID 15801978, 2005). "This attenuation of EGFR signalling by CD82 explains for its recently identified role as metastasis suppressor gene for prostate and pancreatic cancer." (PMID 11953881, 2002). "The most upregulated miRNA from HRH1 stimulation, miR-502–3p, was associated with multiple enriched pathways related to insulin resistance, including EGFR tyrosine kinase inhibitor resistance, AGE-RAGE signaling pathway in diabetic complications, and pancreatic cancer." (PMID 40667070, 2025). "Membrane TF expression was detected in 89% of overall pancreatic cancers and 92% of EGFR-negative pancreatic cancers." (PMID 39751657, 2025). "Moreover, DIM also increased the expression of miR-146 and decreased the levels of epidermal growth factor receptor (EGFR) and nuclear factor-κB (NF-κB), hindering the invasive potential of pancreatic cancer cells." (PMID 41226811, 2025). "Furthermore, the DM001 bsADC demonstrated superior efficacy over its parental monospecific EGFR- and TROP2 ADCs in lung and pancreatic cancer PDXs." (PMID 39065587, 2024). "Furthermore, knockout of MUC1 in tumor cells resulted in higher sensitivity to EGFR inhibitors, and activated EGFR stimulated MUC1 expression in human uterine and pancreatic cancer cell lines." (PMID 39664199, 2024). "Consequently, blocking HER1/EGFR tyrosine kinase signaling has been found to inhibit the growth and metastasis of human pancreatic tumor xenografts and enhance the antitumor effects of gemcitabine." (PMID 38459558, 2024). "Wei Li and team revealed that curcumin effectively suppresses the proliferation and invasive capabilities of pancreatic cancer cells induced by high glucose levels and EGF, primarily through the inhibition of the ERK and Akt pathways and by downregulating EGFR activation." (PMID 38474160, 2024). "EGFR and/or HER2 expression in pancreatic cancers is correlated with poor prognoses." (PMID 38650005, 2024). "Kaempferol treatment significantly downregulated the expression levels of p-EGFR, p-AKT, p-ERK1/2, and Bcl-2, while kaempferol in combination with ERL significantly inhibited pancreatic cancer cell proliferation and induced apoptosis through upregulation expression of caspase-9, PARP, and BAX." (PMID 38324023, 2024). "A study suggested that kaempferol could be a potential therapeutic anticancer agent against pancreatic cancer in combination with erlotinib through the inhibition of the PI3K/Akt signaling pathway and epidermal growth factor receptor (EGFR)." (PMID 37900167, 2023). "Additionally, the mRNA level of CAP1, EGFR and PPARG were identified with significant downregulation in pancreatic cancer cell lines compared to normal pancreatic cells." (PMID 37857015, 2023). "Images were acquired at 0 h and 24 h of EGF treatment (1 ng/mL) alone and combined to treatment with erlotinib, an EGFR kinase activity inhibitor used in therapy of NSCLC and pancreatic cancer, to test the effect of Sorcin silencing in EGFR-dependent migration on H1299 cells." (PMID 37442828, 2023). "Clinical data indicate that targeting EGFR, HER2, and VEGFR receptors may circumvent acquired tumor resistance and improve pancreatic cancer therapeutic outcomes." (PMID 37179357, 2023).
pancreatic cancer (continued). "Combination therapy of lapatinib, an EGFR and HER-2 inhibitor, and capecitabine, a third-generation aromatase inhibitor (AI), showed a tolerable regimen for patients with gemcitabine-refractory pancreatic cancer." (PMID 36975494, 2023). "Kaempferol’s anticancer activity is mediated via inhibition of the EGFR-related Src, ERK1/2, and AKT pathways, and it may be a powerful inhibitor of pancreatic cancer cells." (PMID 37226153, 2023). "Because EGFR and ERBB2 play an important role in PDAC we decided to crossbreed the Trap animals into the well‐established KRASG12D/+ PDAC mouse model to investigate the function of our decoy molecule in pancreatic cancer." (PMID 37341059, 2023). "Our current study identified the change of exosome and lipid metabolism-related genes with clinical value, and the 7-gene (ABCB1, CAP1, EGFR, ITGB1, MAPK1, PPARG, SNCA) prognostic formula is a novel and reliable predictive index in pancreatic cancer and other multiple cancers." (PMID 37857015, 2023). "Importantly, in pancreatic cancer, the YAP/TAZ pathway is downstream from KRAS, PI3K, mTORC1/2, and the epidermal growth factor receptor (EGFR)." (PMID 37432606, 2023). "In addition, sEV carrying members of the EGFR, EpCAM, HER2, MUC1, and Wnt families are also highly sensitive and specific in the diagnosis of pancreatic cancer and can be used as early biomarkers." (PMID 34980146, 2022). "While targeting EGFR with cetuximab and chemotherapy was not successful, the anti-EGFR therapies focus is now on repurposing their use in pancreatic cancer." (PMID 35892707, 2022). "Wnt/β-Catenin, KRAS, EGFR, as well as downstream cellular pathways like MMP and VEGF were found to be downregulated after electrical pulses were applied to pancreatic cancer, and then cancer biology, including proliferation, cell death, invasion, and metastasis, all changed." (PMID 36081554, 2022). "Finally, we analyzed the expression of EGFR, HER2 and VEGFR using immunohistochemistry techniques following intravenous treatment of PDX mouse models bearing human pancreatic cancer tumors." (PMID 36550419, 2022). "Co-targeting STAT3 and EGFR or STAT3 and SRC suppressed cell growth in pancreatic cancer." (PMID 35600368, 2022). "EGFR-targeted NIR-PIT is an excellent candidate for hepatobiliary and pancreatic cancers." (PMID 35453596, 2022). "These conjugates exhibit greater anticancer activity in EGFR- and TfR-positive pancreatic cancer cells than in negative cells." (PMID 36354547, 2022). "In molecular docking, EGFR and MAPK1 were used as receptors, and the active ingredients, quercetin, 17-β-estradiol, ursolic acid, and daidzein, were used as ligands for docking to verify the potential active components and targets of XHP on pancreatic cancer." (PMID 35449823, 2022). "Moreover, the dual inhibition of EGFR/HER2 and IGF-1R signaling did produce stronger antitumor effects than either monotherapies in pancreatic cancer, ovarian cancer, colon cancer, etc.." (PMID 36142299, 2022). "Pancreatic cancer: SELENBP1 is downregulated in pancreatic ductal adenocarcinoma (PDAC) patients with skin rash (SR) treated with erlotinib, an epidermal growth factor receptor (EGFR) tyrosine kinase inhibitor." (PMID 36386843, 2022). "Moreover, treatment by targeting both EGFR and STAT3 was demonstrated to play an important role in EGFR–STAT3 feedback loop blockade and restriction of pancreatic cancer volume." (PMID 35356799, 2022). "It was noted that MYEOV could serve as a ceRNA by producing molecular sponging effects on hsa-miR-103a-3p and hsa-miR-107, thus affecting the role of GPRC5A, SERPINB5, EGFR, KRAS, EIF4G2, and PDCD4 on pancreatic cancer progression." (PMID 36358856, 2022). "Targeted therapy in pancreatic cancer has been successfully evaluated with an EGFR-inhibitor (erlotinib), but was not implemented as a standard of care, mostly due to the marginal benefit in efficacy and toxicity." (PMID 36013144, 2022).
pancreatic cancer (continued). "The cell cytotoxicity of the aptamer–gemcitabine hybrid to the EGFR-positive pancreatic cancer cell line, MiaPaCa-2, has increased significantly but not to the EGFR-negative cell line, HPAF-II." (PMID 36544906, 2022). "Median survival months for EGFR tissue-negative pancreatic cancer patients was 17.00 (8.41–25.59) months." (PMID 35448172, 2022). "Epidermal growth factor receptor (EGFR) is a tyrosine kinase receptor that regulates cell proliferation and differentiation of epithelial cells and tumors, including head and neck, breast, colorectal, lung, and pancreatic cancers." (PMID 34950031, 2021). "The epidermal growth factor receptor (EGFR) plays a key role in regulating cell proliferation, and its overexpression has been observed in several types of cancer, and especially in up to 90% of pancreatic cancer cases." (PMID 35056963, 2021). "Mechanistically, upregulated ciRS-7 was found to inhibit the expression of miR-7 and upregulate the expression of epidermal growth factor receptor (EGFR) and signal transducer and activator of transcription 3 (STAT3), to affect the proliferation and invasion of pancreatic cancer cells." (PMID 33710802, 2021). "Pancreatic cancers without KRAS mutations (about 10% of PDAC) show wild type RAS activation via upstream signaling through receptor tyrosine kinases, including epidermal growth factor receptor (EGFR), which is also required in KRASG12D-driven PDAC." (PMID 34680275, 2021). "Although, overexpression of EGFR in pancreatic cancer was established through numerous evidence but data on the prognostic significance of EGFR expression is still lacking." (PMID 34535145, 2021). "VPA treatment induced expression of ErbB family members-targeting microRNAs (miR-133a, miR-133b, miR-125a, miR-125b, and miR-205) in pancreatic cancer cells without altering mRNAs levels of EGFR, ErbB2, and ErbB3." (PMID 34298623, 2021). "In fact, it was also reported that combined targeting of the epidermal growth factor receptor effector AKT and the glutathione antioxidant pathway mimicked Nrf2 ablation to potently inhibit pancreatic cancer, representing a promising synthetic lethal strategy for treating pancreatic cancer." (PMID 33897415, 2021). "Amongst them, PLD1, EGFR, ST3GAL3 and ARF6 mediate the progression of pancreatic cancer." (PMID 33493138, 2021). "Conversely, a combination of EGFR targeting agents did not offer many clinical benefits in pancreatic cancer patients." (PMID 33918146, 2021). "Moreover, results in this experiment show remarkable synergistic effects observed in pancreatic cancer cells treated with selective STAT3 inhibitors, an EGFR/ErbB2 inhibitor, and a HIF-1α inhibitor." (PMID 33544704, 2021). "Epidermal growth factor receptor (EGFR) inhibition has shown promise in clinical trials of unselected patients with advanced pancreatic cancer, but has not been prospectively tested in KRAS wild-type patients." (PMID 34956889, 2021). "However, ectopic expression of EGFR protein resulted in resistance to 6-P-mediated inactivity of PI3K/AKT signaling and inhibition of malignant phenotype of pancreatic cancer." (PMID 34376189, 2021). "And inhibition of IL‐1β/EGFR/ERK pathway could effectively inhibit NETs‐induced migration, invasion and EMT of pancreatic cancer." (PMID 33955688, 2021). "Moreover, EGFR expression and activation were determined to explore the possible mechanism of AGR2 roles in pancreatic cancer tumorigenesis." (PMID 33413231, 2021). "Experimental models have demonstrated the importance of EGFR activation in KRAS-mutant pancreatic cancer, indicating that RAS/MAPK pathway activation is not sufficient to drive pancreatic tumorigenesis." (PMID 32698506, 2020). "Therefore, EGFR and ERBB2 differentially impact ERBB signaling during pancreatic cancer tumorigenesis, highlighting the need to consider patient’s specific characteristics of ERBB signaling to optimize therapeutic treatment." (PMID 32251323, 2020).
pancreatic cancer (continued). "Of note, our group has previously identified S100A9 to be synergistically regulated by cooperative Hedgehog-EGFR signaling, suggesting a possible role in Hedgehog-dependent malignancies including nonmelanoma skin cancer and pancreatic cancer." (PMID 32503348, 2020). "In this study, we investigated the metabolic alterations in pancreatic cancer cells that do not respond to the EGFR inhibitor erlotinib." (PMID 32974013, 2020). "Moreover, CALR promotes epidermal growth factor (EGF)-triggered EMT via the Integrin/EGFR/ERK/MAPK pathway and alters intracellular Ca2+ levels in the pancreatic cancer cells." (PMID 33221760, 2020). "However, in Cohort 2, which comprised only ductal pancreatic cancer, patients with tumors overexpressing both PODXL and EGFR exhibited a significantly shorter overall survival." (PMID 32587323, 2020). "Moreover, β-AR agonists, especially the β2-AR agonist, activate epidermal growth factor receptor (EGFR) and then Akt and ERK1/2 in a PKA-dependent manner, which in turn upregulate HIF-1α in pancreatic cancer cells even under normoxic conditions." (PMID 33419318, 2020). "MiR-155 knock-down leads to suppression of cell growth and colony formation as well as downregulation of epidermal growth factor receptor (EGFR), membrane-type 1 matrix metalloproteinase (MT1-MMP), and Kirsten rat sarcoma viral oncogene homolog (K-Ras) in pancreatic cancer." (PMID 32489562, 2020). "Our study contained an important distinction from many previous pancreatic cancer studies examining EGFR inhibition in that we did not add exogenous EGF." (PMID 30921351, 2019). "As of yet, epidermal growth factor receptor (EGFR) inhibition has not shown clinical efficacy in pancreatic cancer, but no study has investigated the efficacy of EGFR inhibitors in periampullary adenocarcinoma in relation to morphology." (PMID 32914025, 2019). "Consequently, strategies of ErbB-targeting therapy have been extensively studied, among which agents directed against the EGFR are the best studied targeted agents in pancreatic cancer." (PMID 30961642, 2019). "Moreover, a positive correlation between hRNase5/ANG and EGFR activation was observed in human pancreatic tissue microarrays, supporting the pathological relevance of the hRNase5/ANG-EGFR relationship in pancreatic cancer." (PMID 30449278, 2018). "The majority of targeted therapies against EGFR have not demonstrated the benefit that would have been theoretically expected in clinical trials in patients with advanced pancreatic cancer." (PMID 28445400, 2017). "NCK1 has been demonstrated to affect pancreatic cancer migration but not growth through EGFR, a protein to which our networks also link NCK1." (PMID 29023490, 2017). "Interestingly, our results showed a decrease in EGFR, STAT3, Akt and S6 activities and an increase in ERK activity in 2 CuB-treated pancreatic cancer cell lines." (PMID 29262554, 2017). "We deduce that the combination treatment with CuB and an ERK inhibitor against pancreatic cancer may be more effective than single drug treatment due to complementary effects on STAT3, ERK and EGFR activities." (PMID 29262554, 2017). "This study demonstrated that EGFR expression is not correlated with outcome in resected pancreatic cancer patients." (PMID 27399694, 2016). "As far as we know, there is no precise mechanism, related to EGFR expression regulating the chemotherapy effects, has been reported in pancreatic cancer." (PMID 27399694, 2016).
pancreatic cancer (continued). "The in vitro and in vivo experiments further indicated the combination of AZD8055 and erlotinib synergistically inhibited the mTORC1/C2 signaling pathway, EGFR/AKT feedback activation, and cell growth, as well as suppressed the progression of pancreatic cancer in a xenograft model." (PMID 25654224, 2015). "To determine whether selective silencing of endogenous EGFR led to inhibition of MUC4 mucin expression, we used an EGFR specific siRNA approach in pancreatic cancer cells." (PMID 25686822, 2015). "Therefore, targeting the EGFR and 5-LOX-COX- pathways seems to be a promising approach for the prevention and/or treatment of pancreatic cancer." (PMID 26429877, 2015). "Taken together, these data indicate that simultaneous blockade of IGF-IR and EGFR/Her-2 using NVP-AEW541 and lapatinib may overcome resistance in pancreatic cancer." (PMID 25886138, 2015). "This receptor, along with β-adrenergic receptors, also mediates NNK activation of cellular signals including the enzyme cyclooxygenase-2 (COX2), epidermal growth factor receptor (EGFR) and extracellular-signal-regulated kinases (ERK) in pancreatic cancer cells and ductal cells." (PMID 25938854, 2015). "Briefly, canertinib and afatinib are irreversible pan-EGFR TKIs that have been shown to be effective in various cancers, but its therapeutic efficacy was not explored in pancreatic cancer in the context of MUC4 mucin." (PMID 25686822, 2015). "This hypothesis is supported by a study indicating that CXCR4 could promote EGFR activation and subsequent downstream ERK activation in pancreatic cancer." (PMID 25679210, 2015). "The expression of COX-2 and EGFR in the majority of undifferentiated pancreatic carcinomas suggests that COX-2 and EGFR might represent targets for adjuvant therapy in anaplastic pancreatic cancer." (PMID 26429877, 2015). "Furthermore, HER3 is a key player in tumor cell resistance to EGFR- and HER2-targeted therapies, particularly in pancreatic cancer where it regulates EGFR signaling by modulating the response to erlotinib or cetuximab." (PMID 25216528, 2014). "The downregulation of SOX2 by 6-MITC and I7557 in PANC-1 pancreatic cancer cells harboring mutant K-ras may shed light on elucidating the interaction between SOX2, EGFR, and its downstream KRAS/BRAF and PI3K/AKT pathways." (PMID 24575144, 2014). "We specifically examined the expression of EGFR, a factor overexpressed in pancreatic cancers and the only non-chemotherapeutic marker that has been successfully targeted in the treatment of PDAC." (PMID 25184494, 2014). "HER3-positive pancreatic cancers are more sensitive to erlotinib because it prevents transactivation of HER3 by EGFR and thus inhibits the PI3K/AKT signaling pathway, but not the ERK cascade, which is mainly mutated in pancreatic cancer." (PMID 25216528, 2014). "AM251 (admittedly at higher concentrations) also upregulates the mRNA for both EGFR and its ligands in PANC-1 pancreatic cancer cells, which lack CB1 receptors, so effects (or the lack of them) at higher concentrations of the compound would be very difficult to interpret." (PMID 25012825, 2014). "The recent association of low expression levels of KLF10 with advanced disease in pancreatic cancer, may in part be explained by the repressive action of KLF10 on EGFR expression." (PMID 24429391, 2014). "Since the co-expression of EGFR and MMP-9 has prognostic value in cancer, and Neu1 and MMP-9 cross-talk regulates EGFRs in pancreatic cancer cells, we investigated the molecular targeting potential of the Neu1–MMP9 crosstalk platform in human ovarian cancer cell lines in vitro." (PMID 26932374, 2014). "Signal strength, target gene specificity, and oncogenic activity of HH signaling depend profoundly on interactions with other pathways, such as epidermal growth factor receptor-mediated signaling, which has been shown to cooperate with HH/GLI in basal cell carcinoma and pancreatic cancer." (PMID 23762360, 2013).